RNU6-578P (RNA, U6 small nuclear 578, pseudogene)
Gene: Small nuclear RNA gene on chromosome 4 (12,312,588 to 12,312,690, forward strand). Ensembl gene ENSG00000212282.
Homologues: Orthologues: chimpanzee U6 (92% identical), macaque U6 (83% identical), dog U6 (63% identical), mouse Gm25895 (62% identical), rabbit U6 (61% identical), guinea pig U6 (59% identical), pig U6 (59% identical). Paralogues in human: RNU6-1013P (75% identical), RNU6-209P (75% identical), RNU6-15P (74% identical), RNU6-26P (74% identical), RNU6-621P (74% identical), RNU6-737P (74% identical), RNU6-949P (74% identical), RNU6-1011P (73% identical), RNU6-1024P (73% identical), RNU6-1145P (73% identical), RNU6-1181P (73% identical), RNU6-1241P (73% identical), and 1286 more.